KRT14 (keratin 14)
Diseases named in the same sentence as KRT14 in open-access papers (continued):
Sharing a sentence is not in itself a finding about the gene and the disease.
tumor (392 papers, 2001 to 2026). "Because Krt14-Cre remains active in NC cells, any residual floxed alleles would be deleted during tumor progression, making it highly improbable that a Brd4::Nutm1-positive tumor retains intact Sox2." (PMID 41266112, 2026). "ITGA2hi‐PTC cells were increased in PPTC samples and exhibited high expression of ITGA2, KRT6A, SOSTDC1, KRT6B, and KRT14, genes associated with tumor progression." (PMID 40985182, 2025). "MORC3 deficiency downregulated the E-cadherin (CDH1) tumor suppressive gene and the keratin 14 (KRT14) epithelial differential marker but significantly upregulated the expression of oncogenic JUN, CCND1, CCND2, and CCN1 at the transcriptional level." (PMID 39329063, 2024). "Loss of TGM3 significantly decreased expression of KRT14 in cSCC cells and subcutaneous xenograft tumor models." (PMID 38589352, 2024). "Once the xenograft tumor was established, 10 μg of cytokeratin 14-encoding mRNA LNPs was intranasally instilled in 100 μL PBS once per week for 3 weeks, resulting in a very significant reduction in tumor volume growth compared to the PBS control." (PMID 33478109, 2021). "KRT14-expressing cancer cells were observed in several invasive tumour types, and are specifically associated with invasive cancer cells but absent from the non-invasive component." (PMID 31443478, 2019). "Analysis of the expression levels of the genes in tumor tissue indicated significant associations between the KRT14 (p = 0.034) and ETS2 genes (p = 0.0471) and recurrence." (PMID 25575813, 2015). "Central cells in the MGC samples exhibited downregulation of KRT14 compared with control MGs; loss of KRT14 expression may reflect epithelial-mesenchymal transition of the tumor cells." (PMID 39955307, 2025). "In our studies, we have utilized a keratin 14 (Krt14)-promoter-driven Cre recombinase to delete floxed Pparg in mice to examine how the loss of epidermal Pparg alters tumorigenesis, contact hypersensitivity, and anti-tumor immune responses." (PMID 34445339, 2021). "Importantly, LUAD organoids contained only a marginal number of KRT14+ cells compared to normal lung organoids that is a previously published hallmark of organoids of tumor origin." (PMID 34249925, 2021). "These new approaches combine to show a strong association between invasion and protein expression of Keratin 14, a known biomarker for poor prognosis, with p = 2 × 10−45 for within-tumor tests of individual organoids and p < 10−6 for pooled tests of extreme tails." (PMID 31961880, 2020). "Together, the data suggest that KRT14 expression is a feature of actively invading and migrating cells, and that its loss significantly impedes the ability of spheroids to displace the mesothelium and disseminate during tumour outgrowth." (PMID 31443478, 2019). "Interestingly, these pockets of Cav-1 cells were in close proximity to cells within the tumor expressing high levels of cytokeratin 5 or cytokeratin 14 which were frequently were associated with ghost cells." (PMID 22356861, 2012). "For example, the tumour cell subpopulation BC_P02T demonstrated a high level of KRT14, while the BC_P06T subpopulation was marked by pronounced expression of FABP7, highlighting heterogeneity." (PMID 39877290, 2025). "Among these, KRT14+ epithelial/tumor cells derived from tumor tissue significantly expressed unique BCC-related gene molecular markers, such as BCAM and EPCAM." (PMID 41383502, 2025). "Keratin 14 (KRT14) was identified as a marker of tumor initiating cell subpopulation with stem-like properties in bladder tumorigenesis." (PMID 41145440, 2025). "Differential gene expression analysis demonstrated that Tum_1 tumor cells predominantly expressed basal cell marker genes such as KRT14, KRT5, and KRT15, and exhibited high levels of genes related to cell adhesion, including ITGB4 and ITGA6." (PMID 40470730, 2025).
tumor (continued). "The researchers found that KRT14+ epithelial/tumor cells clustered prominently, and malignant epithelial cells exhibited significant transcriptional heterogeneity." (PMID 41383502, 2025). "Consistently, reduced KRT14 expression was also observed in 4T1ApoA1 cells and tumor tissues obtained from orthotopic models established with these cells." (PMID 38566092, 2024). "Of note, the median expression value of TBX1 was greatest in the KRT14+ high TM group compared to the other 32 TCGA pan‐cancer tumor types." (PMID 39258580, 2024). "The expression of RSPO3, ALPP, VEGFC, ANXA8, HES2, GLP2R, and KRT14 in normal tissues was significantly higher than that in tumor tissues." (PMID 38240936, 2024). "They found that high KRT14 and low FOXA1 were expressed in basal subtypes, while luminal tumours had low KRT14 and high FOXA1, categorising micropapillary, nested, and plasmacytoid carcinoma as luminal." (PMID 39594166, 2024). "In BrM, we also identified four tumor cell clusters, termed Tumor_A-D, stratified based on expression of EpCAM, cytokeratin 8, cytokeratin 14, and E-cadherin." (PMID 38622132, 2024). "In this tumor model, we found that the DMBA induced tumor cells predominantly originated from Krt14+ basal cells, and the mammary cells showed prominent age-related susceptibility to chemical induced cancer transformation." (PMID 38886378, 2024). "High concordance was observed between primary tumours and lymph node metastases using an IHC panel for subtype classification, with high concordance for KRT14 in the Ba/Sq subtype." (PMID 39594166, 2024). "Although MMTV-PyMT tumour organoids initially display low numbers of KRT14+ cells, the formation of invasive tumour strands is proceeded by the acquisition of KRT14 expression at the leading edge." (PMID 39408880, 2024). "Remarkably, compared to control tumours which were KRT8 and pAMPK positive, GPx2 KD tumours contained KRT8/KRT14 positive areas that expressed pAMPK (in the cytosol) and GLUT1 (at the membrane) in same cells." (PMID 38238426, 2024). "It is abundantly appearing in the leading edge of invasive tumor cells and KRT14+ cells are suggested to have an essential role in the collective cancer cell dissemination." (PMID 38597967, 2024). "Luminal-like tumor cells were identified by Krt8 expression, whereas basal-like tumor cells were identified by either Krt5 or Krt14 expression." (PMID 36859337, 2023). "There were very low levels of membranous PD‐L1 staining in most of the analysed tumours (0–5% of keratin 14‐positive area)." (PMID 37443405, 2023). "In the present case, IHC examination of the tumor revealed that vimentin was positively stained, P63, KRT14, S-100 was focally positive, Ki-67(80%), while KRT5/6, KRT7, GFAP, calponin, SMA, KRT-PAN, SOX10, mammaglobin was negative." (PMID 37705036, 2023). "HCA showed low activation of CASP3 and CASP8, ranging between 0–6% and 0–10% of the tumour (keratin 14‐positive) area respectively." (PMID 37443405, 2023). "Class 3 tumours show some of the gene expression characteristics associated with MIBC (KRT5+, KRT14+, CD44+, KRT20− and PPARG−)." (PMID 36928373, 2023). "This presents a convenient test case for SpatialCorr and we indeed identified strong correlation between expected type 1 and type 2 pairs such as KRT1 and KRT10, as well as KRT5 and KRT14, throughout the epidermis and much of the tumor." (PMID 36590683, 2022). "The expression of both H3K27me3 and KRT14 increases in splenic metastatic cells compared to primary tumor cells, confirming the positive correlation between H3K27me3 and KRT14 in TNBC splenic metastasis in a preclinical animal model." (PMID 36446780, 2022). "Most of the TMEM119+ FIBs appeared to be positioned peripherally and juxtaposed to KRT14+ tumor nests, to a greater extent than those observed for CLIC2+ and CEMIP+ FIBs or sparse ASPN+ FIBs." (PMID 35687691, 2022).
tumor (continued). "KRT14+ epithelial/tumor cells from BCC-III showed a “hybrid” position where many cells significantly overlapped with the PTS samples, whereas other cells uniquely clustered singly, matching our previous observations with InferCNV analyses." (PMID 35687691, 2022). "After extensive in vitro validation, we sought to determine the correlation between H3K27me3 and KRT14 expression in vivo by confocal microscopy in isolated primary tumor cells versus splenic metastatic cells." (PMID 36446780, 2022). "After extensive validation, KRT14 was found to be the markedly upregulated gene in the cells isolated from lung, liver, and splenic metastasis as compared to primary tumor cells, though the highest robustness was observed in the case of splenic metastasis." (PMID 36446780, 2022). "To identify signaling differences between the BCC and PTS microenvironments, we probed the human BCC FIB-epithelial interactome by modeling single cell-cell interactions among KRT14+ epithelial/tumor and FIB/FIB-like cells using CellChat." (PMID 35687691, 2022). "The differential expression between tumor and adjacent tissues expression levels displayed for KRT14, KRT16, KRT17, and KRT6B indicated that their expression levels were higher in normal tissues than in tumors." (PMID 36293530, 2022). "All tumor cells from the different groups were positive for the epidermal basal cell marker keratin 14 (K14), which is normally expressed in the oral stratum basal layer (undifferentiated cells)." (PMID 33539340, 2021). "Multicolor lineage tracing in mouse models demonstrated that polyclonal lung metastases arise from collective dissemination of cell clusters containing keratin 14‐expressing tumor‐initiating cells." (PMID 33932112, 2021). "We previously reported that keratin 14 (K14) promoter-driven expression of MCC tumor-derived MCPyV small T and truncated LT antigens in murine skin promotes severe epithelial phenotypes." (PMID 33435392, 2021). "A very small proportion of PyMT cells can also be found within both of these clusters and the presence of basal cells (KRT14+ leader cells or CD29hi cells) have been described in this tumor model." (PMID 32840210, 2020). "mRNA expression of the two basal-type markers KRT6A and KRT14 as well as EGFR confirmed comparable levels between the original tumor tissue and p-SCC." (PMID 32978523, 2020). "Similar correlations have been observed in other tumour types, where the KRT14-expressing cell subset is increased in urothelial cancers in response to chemotherapy." (PMID 31443478, 2019). "Here we provide additional pieces by reporting on changes in lifespan and tumor incidence that accompany IGF1 expression driven by keratin-14 promoter in FVB/N-derived transgenic K14/mIGF1 female mice." (PMID 30981207, 2019). "Tumor expression profile included an upregulation of basal cell markers such as Krt5, Krt6, Krt14 and Krt1 as well as Cdh3 and Cd44." (PMID 31779626, 2019). "The two group 1 tumors with elevated levels of cell cycle/proliferation genes tend to express KRT14 more than the others, and the tumor with the highest KRT14 level was the only one positive for CK14 by IHC staining." (PMID 30699951, 2019). "The tumor tissue structure of the explants was examined by hematoxylin and eosin (H&E) staining and tumor marker of cytokeratin 14 expression." (PMID 30723707, 2019). "This metaplasia expressed high levels of p63 and cytokeratin 14 (CK14) and was usually localized close to a tumor." (PMID 29463648, 2018). "We evaluated tumor growth, cytokeratin-8 (K8)-positive luminal cells, cytokeratin-14 (K14)-positive myoepithelial cells, and expression of AREG, Ki67, and PyMT." (PMID 30367629, 2018). "Our data supported that the constitutive activation of MEK2 was sufficiently induced tumor formation in Tg(krt14:MEK2S219D-GFP) transgenic zebrafish." (PMID 26572230, 2015).
tumor (continued). "The tumor cells stillexpressed ERα but there was lower keratin 8/18 and higher keratin 14 staining asthe cells migrated from the ducts into the stroma." (PMID 25527189, 2014). "Although Cav-1 failed to completely co-localize with either cytokeratin 5 or cytokeratin 14, most of the Cav-1 positive cells were found in regions of the tumor were there was an abundance of cytokeratin 5 or cytokeratin 14 positive cells." (PMID 22356861, 2012). "Some tumor nests were rimmed by myoepithelium positive for smooth muscle actin, p63, and cytokeratin 14, indicating the presence of intraductal components of the tumor." (PMID 22151879, 2011). "To further investigate this difference we stained the tumour margins for keratin 14 to unambiguously identify the tumour cells and laminin to stain any structures resembling basement membranes." (PMID 15597106, 2005). "To confirm that integrin β1 remained stably knocked down in vivo we stained frozen sections of the tumours for integrin β1, keratin 14 to identify tumour cells and CD31 to identify endothelial cells." (PMID 15597106, 2005). "Also, it has been reported that at the initial steps of the metastatic cascade, disseminated tumor cells exhibit stem-like transcriptional features, and that cell clusters containing KRT14 + cells have a high metastatic ability." (PMID 40676433, 2025). "Myoepithelial cells surround the ductal epithelium for structural support, and our results also showed that myoepithelial cell markers, including ACTA2, MYLK, and KRT14, were enriched in the perispatial domain of the tumor, suggesting high-quality detection of tumor contours using our algorithm." (PMID 39965034, 2025). "KRT14, a member of the keratin family of intermediate filament proteins, could be an indicator of the remodeling of the gastric epithelium, promoting tumor growth and invasion." (PMID 41155404, 2025). "However, in agreement with feature plots, GPx2 KD tumours harboured areas expressing both E and M markers involving KRT14 (basal) and KRT8 (luminal) relative to control tumours expressing only KRT8 (Areas 1, 3, 4)." (PMID 38238426, 2024). "Additionally, we observed an elevated expression of KRT14 in tumor tissue from the mice fed either a Western diet or a high-cholesterol diet." (PMID 38566092, 2024). "Furthermore, TGM3 serves as a novel cSCC tumor differentiation marker through binding to KRT14 and promoting its degradation." (PMID 38589352, 2024). "Interestingly, these tumours harboured significantly less KRT8/KRT14 or E-CAD/VIM positive areas than vehicle-treated GPx2KD tumours, due to mesenchymal gene repression." (PMID 38238426, 2024). "Interestingly, PyMT2 tumours were enriched in KRT8/KRT14 or E-CAD/VIM hybrid areas as compared to GPx2 OE tumours which expressed either KRT8 or E-CAD, indicative of mesenchymal to epithelial transition (MET)." (PMID 38238426, 2024). "Indeed, PyMT2/gRNA2 tumours were luminal-like (KRT8+ or E-CAD+), as compared to control tumours which were E/M-like as shown by KRT8/KRT14 or E-CAD/VIM expression." (PMID 38238426, 2024). "Interestingly, GPx2 KD tumours also harboured areas that were either KRT14 or KRT8 positive (Area 2)." (PMID 38238426, 2024). "Moreover, p63 was mostly co-localised with KRT8 and KRT14 in GPx2KD tumours and this pattern was recapitulated in distant mets." (PMID 38238426, 2024). "Deguelin also reversed TGM3 knockdown-induced KRT14 higher expression in xenograft tumor models." (PMID 38589352, 2024). "Indeed, echinomycin-treated GPx2 KD tumours showed dramatic reductions in p63 and KRT14 levels, resulting in KRT8-enriched tumours, indicative of luminal differentiation." (PMID 38238426, 2024). "Similarly, GPx2 OE tumours, showed high E-CAD and low N-CAD/KRT14/VIM expression relative to control PyMT2 tumours." (PMID 38238426, 2024). "In various tumors, KRT14 was widely expressed in malignant cells in the tumor microenvironment." (PMID 37169018, 2023).
tumor (continued). "A count of the micrometastases (KRT14 positive cells) in the lungs indicated that treatment of mice with APPI‐3M‐HSA significantly reduced the number of metastatic lesions vs. the number in the lungs of tumor‐bearing mice treated with PBS." (PMID 37609678, 2023). "On the other hand, Krt14 expression was more abundant throughout the tumor, indicating that Krt14 could serve as a more appropriate marker to track basal identity within these tumors." (PMID 36859337, 2023). "In situ, CLIC2+ FIBs are located sparsely surrounding KRT14+ tumor cell nests." (PMID 35687691, 2022). "Gene intersection and survival analysis showed that there were 435 DEG crosses in PTC patients and genome-wide tumor samples, only CXCL10, CD40LG, KRT14, TRAT1, and TREM2 were associated with patient prognosis, and TCGA showed that only the TREM2 expression was upregulated in PTC." (PMID 36438899, 2022). "Non-PTS KRT14+ epithelial/tumor cells uniquely expressed known BCC-associated gene biomarkers including BCAM and EPCAM." (PMID 35687691, 2022). "Similarly, KRT14 is the only robustly upregulated gene in Y641-F cells compared to control cells in vitro and primary tumor versus splenic metastatic cells in vivo, following orthotopic inoculation of wild-type cells." (PMID 36446780, 2022). "Because TMEM119+ FIBs segregated distinctly across KRT14+ tumor nests and were significantly higher in proportion in BCC samples, we wondered whether they may have a unique gene expression profile that may functionally support tumoral growth and progression." (PMID 35687691, 2022). "Tumors of control and ACK1 ko mice showed increased expression of the basal keratinocyte marker keratin‐14 (K14), which might be due to an increased percentage of basal keratinocytes in the tumors compared with tumor‐free skin." (PMID 33730447, 2021). "This was validated in transgenic mouse models in which individual HPV oncoproteins, alone or in combinations, were expressed under the control of the epithelial-specific keratin-14 (K14) promoter; tumour formation was greater in mice expressing E5/E6 or E5/E7 when compared with E6 or E7 alone." (PMID 32899142, 2020). "A new study using a 3D microfluidic device that enables real‐time imaging of mammalian cell clusters during migration characterised the dynamics of leader and follower cells and found that pre‐existing keratin 14 (K14)‐positive cells in a tumour organoid have the potential to become leader cells." (PMID 32057095, 2020). "KRT14 mRNA expression was measured in bulk cells from clinical specimens including (i) primary tumour tissue; (ii) ascites-derived HGSC cells; (iii) benign cells; (iv) histologically normal ovary; and (v) the target peritoneal cell layer LP9 alone (n = 3 per group)." (PMID 31443478, 2019). "It is likely that the combination of ECM composition and effector molecules produced by mesothelial cells are an active participant in KRT14+ cell-mediated invasion, and establish a microenvironment that is permissive for tumour deposition and invasion within the peritoneal cavity." (PMID 31443478, 2019). "The scaffold-free edge retains the original tumour architecture showing the characteristic reverse bilayer phenotype of Wnt1 tumours where basal cells, defined by their expression of cytokeratin-14 (CK14), α-smooth muscle actin (αSMA) and nuclear p63, line the lumen (i-iii, lumen marked as*)." (PMID 30139956, 2018). "Although cytoplasmic Yap1 could be detected in all tumor cells, strong nuclear expression of Yap1 was detected specifically in Krt14-positive TICs." (PMID 26695440, 2016). "Immunofluorescence of PE tumor cells derived either directly from the patient or after culturing for 96 hours demonstrated the presence of both luminal (keratin-8 positive) and basal (keratin-14 positive) cell types." (PMID 23879992, 2013).